RETN (resistin)
Diseases named in the same sentence as RETN in open-access papers (continued):
Sharing a sentence is not in itself a finding about the gene and the disease.
asthma (continued). "High resistin levels predicted favourable anti-inflammatory effect of inhaled glucocorticoids suggesting that resistin may be a marker of steroid-sensitive phenotype in asthma." (PMID 21615949, 2011). "Therefore resistin may have a role as a factor or a predictor in steroid-responsive asthma." (PMID 21615949, 2011). "In the study of children with asthma, the level of resistin was lower in atopic asthmatics compared to nonatopic asthmatics and healthy controls." (PMID 38542187, 2024). "Resistin/adiponectin ratio was not affected by sex, degree of asthma severity or level of asthma control in either normal weight or overweight/obese asthmatic." (PMID 37149591, 2023). "The current study was designed to examine the circulating apelin, resistin, and visfatin levels in children with AD, who had no current additional allergic symptoms such as asthma and allergic rhinitis." (PMID 23476106, 2013). "However, specific receptors for resistin have not yet been determined, and its actual role in asthma remains inconclusive." (PMID 38542187, 2024). "In non-obese women with newly-diagnosed steroid-naïve asthma, high resistin levels predicted favourable anti-inflammatory effect of inhaled glucocorticoids suggesting that resistin may be a feature and biomarker of steroid-sensitive phenotype of asthma." (PMID 21615949, 2011). "In the present study including non-obese women with newly diagnosed steroid-naïve asthma, we found that baseline resistin concentrations correlated with anti-inflammatory effects of inhaled fluticasone suggesting that resistin may be a feature and biomarker of steroid-sensitive phenotype of asthma." (PMID 21615949, 2011). "The median concentration in LC patients compared to healthy non-smokers, asthma sufferers, and smokers was more than 200% higher in SAA (771%), MMP-9 (743%), IL-8 (535%), CXCL9/MIG (482%), TNFRI (406%), Gro (331%), MPO (300%), Rantes (274%), Resistin (271%), TNFRII, and MIF (219%)." (PMID 32085733, 2020).
COVID-19 (27 papers, 2021 to 2025). A disease caused by infection with severe acute respiratory syndrome coronavirus 2. "Lipocalin-2 and resistin levels were higher in the placenta, revealing an underlying pro-inflammatory status in the gestation period for mothers suffering from COVID-19." (PMID 38610889, 2024). "The difference in leptin, adiponectin, and resistin gene/protein expression in abdominal visceral or subcutaneous adipose tissue and their relationship with long COVID-19 symptoms risk merits be discussed." (PMID 39469144, 2024). "Ebihara and colleagues provided additional evidence for the association of high circulating resistin levels with COVID-19 disease severity and survival." (PMID 37238973, 2023). "A very recent paper found resistin levels elevated in COVID-19 patients are also associated with cytokines and endothelial cell adhesion molecules and related to a worse outcome." (PMID 36674646, 2023). "The analysis revealed that patients with high levels of resistin and IL-15 were at a high risk of suffering more severe COVID-19 symptoms; in concrete, they would more probably require invasive ventilation." (PMID 35330391, 2022). "Resistin and these four cytokines were measured in the present study, and COVID-19 patients showed increased plasma resistin levels and an association with these cytokines." (PMID 35784283, 2022). "In the present study, we showed that ICAM-1 and VCAM-1 were elevated more in COVID-19 patients than in controls and were associated with resistin levels." (PMID 35784283, 2022). "The most relevant results are that resistin, IL-6, IL-8, IL-15, IL-18, MCP-1 and TNF-α are the main cytokines associated to COVID-19 symptomatology; meanwhile resistin, IL-8, IL-15, MCP-1 and TNF-α used to be associated with oxygen therapy necessity." (PMID 35330391, 2022). "Resistin was elevated in COVID-19 and was associated with both cytokines and endothelial cell adhesion molecules." (PMID 35784283, 2022). "Resistin was elevated in COVID-19 patients and was associated with cytokines and endothelial cell adhesion molecules." (PMID 35784283, 2022). "In line with our results, resistin was elevated in COVID-19 patients, and associated with cytokines and endothelial cell adhesion molecules, while also being related to a worse clinical course in patients with COVID-19." (PMID 36289725, 2022). "Finally, we performed a multivariate analysis to discriminate the potential interference of other factors; after adjusting for BMI, glucose, cholesterol, and triglycerides, the levels of serum adiponectin and resistin were significantly associated with COVID-19 (p < 0.001 for both)." (PMID 36674646, 2023). "Mechanistic studies are recommended to further elucidate the importance of metabolic vs immune modulation by resistin in COVID-19, to identify future therapeutic targets." (PMID 40352457, 2025). "It has been previously reported that resistin levels were higher in patients suffering COVID-19; it is also known that resistin enhances the NF-kB transcription factors leading to higher expression of pro-inflammatory cytokines and cytokine storms in COVID-19." (PMID 38610889, 2024). "The levels of resistin were found to be increased in individuals diagnosed with COVID-19, and this elevation was found to be correlated with the presence of cytokines and endothelial cell adhesion molecules." (PMID 38255708, 2024). "Lipocalin-2 and resistin levels were higher in the placental tissue (p < 0.05 and p < 0.01, respectively) of mothers suffering from COVID-19 compared with the control group." (PMID 38610889, 2024). "With regard to colostrum, adiponectin, resistin, and insulin concentrations showed an increase in the COVID-19 group (p < 0.01, p < 0.01, and p < 0.05, respectively) compared with the control group." (PMID 38610889, 2024).
COVID-19 (continued). "Resistin was also measured in the current study, showing—for the first time in the literature that we had studied—that mothers who suffered COVID-19 had increased levels of resistin in their placenta and colostrum." (PMID 38610889, 2024). "Higher resistin levels were detected in 159 severely ill and 71 critically ill COVID-19 patients, compared to 30 patients with mild symptoms." (PMID 37238973, 2023). "Plasma resistin amounts were markedly induced in COVID-19 patients admitted to the intensive care unit in comparison to less ill patients and asymptomatic controls." (PMID 37238973, 2023). "When compared to healthy subjects, total adiponectin levels were statistically lower in severe COVID-19 while, in contrast, the levels of leptin and resistin were statistically higher." (PMID 36674646, 2023). "In severe COVID-19 patients, IL-6 levels positively correlated with the levels of Adiponectin, Visfatin, Resistin and negatively correlated with plasma leptin levels." (PMID 36509969, 2023). "The literature data available on resistin in COVID-19 showed, in accordance with our data, that resistin is higher in COVID-19 patients and predicts the requirement of invasive ventilation." (PMID 36674646, 2023). "In this study, we found that resistin levels are higher in COVID-19 patients compared to healthy controls and are able to predict COVID-19 disease, as demonstrated by the ROC curve analysis." (PMID 36674646, 2023). "In this scenario, the aim of this study was to investigate the serum levels of adiponectin, its HMW oligomers, leptin, and resistin in severe COVID-19 patients, focusing on their correlation with clinical and biochemical patient parameters." (PMID 36674646, 2023). "Our published data, in accordance with few available data in the literature, showed that resistin is higher in COVID-19 patients and has been found to predict the requirement for invasive ventilation." (PMID 37686837, 2023). "Regarding the prediction of the COVID-19 outcome, using different methods, we found that IL-15 and resistin were the best predictors of the requirement of invasive ventilation." (PMID 35330391, 2022). "In the present study, resistin gene expression in whole blood cells was elevated, suggesting that these cells were responsible for the production of resistin in COVID-19 patients." (PMID 35784283, 2022). "Among the cytokines analyzed, those that correlated with a worse prognosis of COVID-19 were resistin, IL-6, IL-8, IL-15, MCP-1 and TNF-α." (PMID 35330391, 2022). "Intriguingly, we noticed relatively higher expression levels of anti-inflammatory (IL1R2) and immune suppressive (RETN) genes in MDSC monocytes of hospitalized COVID-19 patients with the use of ACEis; consistent with the immunosuppression function of MDSCs." (PMID 36817759, 2022). "The mRNA expression of resistin in whole blood in the COVID-19 patients of the Osaka cohort was significantly higher than that in the controls." (PMID 35784283, 2022). "Several studies have shown that COVID-19 in obese people can lead to significant behavioral changes in adipokines (increase in leptin, decrease in adiponectin, increase in resistin, and decrease in omentin)." (PMID 36497720, 2022). "RETN gene expression in monocytes was significantly up-regulated (q < 0.0002) in COVID19-ACEi compared to COVID-19- only." (PMID 36817759, 2022). "The genes that are up-regulated in COVID19-ACEi, IL1R2 and RETN were clustered with markers of COVID-19 immunopathology, SPO2, and 3 other down-regulated genes." (PMID 36817759, 2022). "This is the first study, to our knowledge, to identify an association between resistin, cytokines and endothelial damage markers, and also to identify the relationship between resistin and disease severity and clinical outcome, in COVID-19 patients." (PMID 35784283, 2022).
COVID-19 (continued). "In comparison to those of the healthy controls, the plasma resistin levels of the COVID-19 patients in the Osaka cohort 2 were significantly higher on day 1, days 2-3 and days 6-8." (PMID 35784283, 2022). "A prospective observational study reported that high concentrations of resistin were associated with worse clinical outcomes and more pronounced inflammation in COVID-19 patients, while leptin and adiponectin were not." (PMID 39469144, 2024). "Moreover, there was a positive correlation observed between elevated levels of resistin and unfavorable clinical outcomes in individuals diagnosed with COVID-19." (PMID 38255708, 2024). "Plasma resistin levels in COVID-19 patients are elevated compared to healthy controls." (PMID 37238973, 2023). "The results indicated that resistin could predict the clinical outcome of COVID-19 patients regarding the need of MV (p < 0.001)." (PMID 35330391, 2022). "The data on the role of resistin and adiponectin in COVID-19 are scarce." (PMID 36289725, 2022). "Higher resistin levels were related to a worse clinical course in patients with COVID-19." (PMID 35784283, 2022). "Resistin and inflammatory cytokines could be stimulated by each other, thus leading to a cytokine storm in COVID-19." (PMID 35784283, 2022). "Therefore, resistin and IL-15 should be included in the personalized treatment decision algorithm of patients with COVID-19." (PMID 35330391, 2022). "Moreover, ROC curves revealed that resistin was the best predictor of MV necessity in COVID-19 patients." (PMID 35330391, 2022). "Therefore, resistin could have a key role both in COVID-19 and MASLD which have, as an element in common, alterations in hemostasis." (PMID 38255708, 2024). "Corroborating that resistin levels could be a useful marker for COVID-19 disease outcome, it was identified in a cohort of 254 COVID-19-infected patients that serum resistin levels were higher in patients with severe disease compared to those patients with non-severe disease on the day of admission." (PMID 37238973, 2023). "Therefore, longitudinal studies investigating circulating Visfatin and Resistin in COVID-19 patients might shed more light on the role of adipokines and critical illness severity and patient outcome." (PMID 36509969, 2023). "However, leptin was shown to induce expression of resistin and galectin-3, and thereby may contribute to higher levels of resistin and galectin-3 in the serum of COVID-19 patients." (PMID 37238973, 2023). "Therefore, this study aimed to evaluate whether resistin is involved in the pathogenesis of COVID-19." (PMID 35784283, 2022). "We measured the adipocytokines levels (Adipokines, Adipsin, Resistin, Leptin, Visfatin and Plasminogen Activator Inhibitor-1 (PAI-1)) in acute, convalescent COVID-19 and control children." (PMID 37013538, 2023). "Several studies provided insights on chemerin, adiponectin, leptin, resistin, and galectin-3 levels in SARS-CoV-2-infected patients, while limited information is yet available on the adipokines apelin and visfatin in COVID-19." (PMID 37238973, 2023). "If several evidences confirm that a hyperinflammatory signature characterizes monocytes from COVID-19 patients, other data prove that an immunosuppressive signature, defined by downregulation of HLA-DRA, ALOX5AP, and RETN, also exists." (PMID 35710943, 2022). "We also described the correlation of inflammatory cytokine levels (resistin, IL-6, IL-8, IL-15, MCP-1 and TNF-α) with clinical variables related to a worse COVID-19 prognosis." (PMID 35330391, 2022). "With regard to colostrum, adiponectin, resistin, and insulin concentrations showed an increase, while a decrease in GLP-1, leptin, and PYY was also reported in the colostrum of mothers suffering from COVID-19 compared with the control group." (PMID 38610889, 2024).
COVID-19 (continued). "Recent researchers showed, regardless of normal-weight and obese women of COVID-19 patients, the expression levels of resistin were high in SF, but leptin and adiponectin are both low." (PMID 39469144, 2024). "As for adiponectin, resistin, and insulin, their concentrations showed an increase; a decrease in GLP-1, leptin, and PYY was also reported in the colostrum of mothers suffering from COVID-19 compared with the control group." (PMID 38610889, 2024). "In severe, but not critical COVID-19 patients, we found that plasma Leptin, Resistin and IL-6 correlated with the fraction of inspired oxygen (FiO2) but not the length of hospital stay." (PMID 36509969, 2023). "On admission, there were higher serum concentrations of tumor necrosis factor α (TNFα) (p < 0.001), interleukin 1 β (IL-1β) (p < 0.001), pentraxin 3 (PTX3) (p < 0.001), resistin (p = 0.032), and lower concentrations of adiponectin (p < 0.001) between the severe COVID-19 and the non-severe patients." (PMID 36289725, 2022). "The results of the existing studies are often inconsistent, with some studies reporting higher levels of chemerin, resistin, adiponectin, while others show lower levels of chemerin, and similar concentrations of adiponectin in COVID-19 patients as compared with non-COVID-19 patients." (PMID 36289725, 2022). "Strikingly, and showing marker potential for disease progression and outcome, high plasma resistin levels of non-critically ill COVID-19 patients were characteristic for those patients that progressed to severe illness and were less likely to survive the COVID-19 disease." (PMID 37238973, 2023).
Arthritis (25 papers, 2012 to 2023). Inflammation of a joint. "Adipokines leptin, adiponectin and resistin have recently been associated with inflammation and cartilage destruction in arthritis." (PMID 25333960, 2014). "Treatment with metformin, alendronate, and their combination decreased serum concentrations of leptin and resistin in the chronic phase of arthritis." (PMID 34440221, 2021). "In particular, resistin was shown to accumulate in the inflamed joints of RA patients and to induce the development of arthritis accompanied by leukocytic infiltration and hyperplasia of the synovium following injection into the joints of healthy mice." (PMID 33192583, 2020). "In a mouse study, the intra-articular injection of resistin can induce arthritis, suggesting that resistin is a pro-inflammatory cytokine." (PMID 33014539, 2020). "Resistin upregulates the expression of inflammatory cytokines and chemokines in chondrocytes, and intra-articular resistin injection induces arthritis in healthy mouse joints." (PMID 30809105, 2019). "Other adipokines, such as visfatin and resistin, also play important roles in arthritis pathogenesis." (PMID 30917508, 2019). "This treatment yielded a significant improvement of arthritis and physical function in most patients and a decline of acute phase reactants and of resistin, adiponectin, TNF-α, and especially IL-6 levels." (PMID 26526677, 2016). "We did not observe an association between serum levels of adiponectin, leptin, chemerin, resistin, or omentin and the subsequent development of clinically manifest arthritis." (PMID 26670468, 2015). "Resistin has been found in the plasma and synovial fluid of RA patients, and injection of resistin into mice joints induces an arthritis-like condition, with leukocyte infiltration of synovial tissues, hypertrophy of the synovial layer, and pannus formation." (PMID 22910888, 2012). "Furthermore, the hypothesis of pro-inflammatory resistin function was confirmed by the development of arthritis after resistin injection into the joints of healthy mice." (PMID 22584415, 2012). "Only a few articles have reported that serum resistin levels do not significantly differ among RA and OA patients and those without arthritis (12.1, 10.8, and 10.0 ng/mL, respectively)." (PMID 30809105, 2019). "Expression of adiponectin, resistin and visfatin in the synovium was not only observed in individuals who developed arthritis after follow-up, but also in those who did not." (PMID 26670468, 2015). "A small number of studies have been performed to address the role of resistin in T cell functions, but recent evidence has showed that resistin strongly up-regulates the expression of TNF and IL-6 by human PBMCs and induces arthritis after injection into the joints of healthy mice." (PMID 24151494, 2013). "As previously reported, arthritis induced a marked decrease in serum concentrations of adiponectin and leptin, whilst serum resistin was not significantly decreased." (PMID 23781298, 2012). "In contrast to serum adiponectin and leptin concentrations, arthritis, fenofibrate treatment, or pair-feeding the rats did not change serum concentration of resistin." (PMID 23781298, 2012). "The authors could not prove differences in resistin levels in the groups with and without arthritis." (PMID 37355349, 2023). "There will be always much more information that could be introduced as variables to adjust for (medication, arthritis, etc.)but, to our knowledge, there is not any described factor that can influence resistin in the general population and modify our results." (PMID 28771611, 2017). "Arthritis decreased serum leptin, adiponectin, and insulin (P<0.01) but not resistin levels." (PMID 23781298, 2012). "The resistin levels were not significantly different between patients with and without arthritis or patients with and without interstitial lung disease although these compartments may be a potential source of resistin." (PMID 22577940, 2012).